TRBV11-2 (T cell receptor beta variable 11-2)
Description:
V region of the variable domain of T cell receptor (TR) beta chain that participates in the antigen recognition. Alpha-beta T cell receptors are antigen specific receptors which are essential to the immune response and are present on the cell surface of T lymphocytes. Recognize peptide-major histocompatibility (MH) (pMH) complexes that are displayed by antigen presenting cells (APC), a prerequisite for efficient T cell adaptive immunity against pathogens. Binding of alpha-beta TR to pMH complex initiates TR-CD3 clustering on the cell surface and intracellular activation of LCK that phosphorylates the ITAM motifs of CD3G, CD3D, CD3E and CD247 enabling the recruitment of ZAP70. In turn ZAP70 phosphorylates LAT, which recruits numerous signaling molecules to form the LAT signalosome. The LAT signalosome propagates signal branching to three major signaling pathways, the calcium, the mitogen-activated protein kinase (MAPK) kinase and the nuclear factor NF-kappa-B (NF-kB) pathways, leading to the mobilization of transcription factors that are critical for gene expression and essential for T cell growth and differentiation. The T cell repertoire is generated in the thymus, by V-(D)-J rearrangement. This repertoire is then shaped by intrathymic selection events to generate a peripheral T cell pool of self-MH restricted, non-autoaggressive T cells. Post-thymic interaction of alpha-beta TR with the pMH complexes shapes TR structural and functional avidity.
Synonyms: TCRBV21S3A2N2T; TRBV112; TCRBV11S2
Gene: Protein-coding gene on chromosome 7 (142,433,895 to 142,434,394, forward strand). Ensembl gene ENSG00000241657.
Subcellular location: Cell membrane
Gene Ontology:
Biological process: cell surface receptor signaling pathway
Cellular component: plasma membrane
Homologues: Orthologues: macaque TRBV11-2 (90% identical), chimpanzee TRBV11-2 (83% identical), mouse Trbv14 (64% identical). Paralogues in human: TRBV11-1 (85% identical), TRBV11-3 (83% identical), TRBV7-3 (64% identical), TRBV7-2 (63% identical), TRBV7-9 (60% identical), TRBV7-1 (59% identical), TRBV7-7 (59% identical), TRBV7-6 (58% identical), TRBV7-4 (57% identical), TRBV12-5 (55% identical), TRBV12-4 (54% identical), TRBV14 (53% identical), and 39 more.